METTL1 (methyltransferase 1, tRNA methylguanosine)
Diseases named in the same sentence as METTL1 in open-access papers (continued):
Sharing a sentence is not in itself a finding about the gene and the disease.
tumor (continued). "As a tRNA m7G methyltransferase, METTL1 plays a pivotal role in regulating HCC cell proliferation and tumor development." (PMID 41562049, 2025). "Next, to further confirm the effect of METTL1 on the lymph node metastasis of PTC cells in vivo, we established a nude mouse model of the lymph node metastasis of tumor cells injected into the footpad." (PMID 40360483, 2025). "METTL1/WDR4 indirectly promotes partial mRNA translation efficiency through high-frequency m7G tRNA decoding codons, impacting stem cell self-renewal, tumor progression, and drug resistance." (PMID 40809690, 2025). "The resulting lactate accumulation transactivates METTL1 expression via H3K9 lactylation, establishing a METTL1-PKM2-H3K9la metabolic‒epigenetic regulatory loop that promotes tumor proliferation." (PMID 40859309, 2025). "In this study, we discovered that METTL1 boosts BRCA1 expression through m7G modification, thereby facilitating cell proliferation and tumor growth in HGSOC." (PMID 41430564, 2025). "Several investigations have indicated that METTL1 plays a role in the TME, influencing tumor immunity." (PMID 40809384, 2025). "Human CXCL8 translation was specifically controlled by METTL1-mediated m7G tRNA alteration, allowing MDSC to accumulate in the tumor immunological environment to accelerate ICC progression in vivo." (PMID 38641828, 2024). "Therefore, METTL1 may act as a target to enhance the anti‐tumor activity of EGFR‐TKIs." (PMID 38967523, 2024). "In this review, we not only focus on the structure and mechanism of m7G modified writers METTL1 and WDR4, as well as reader QKI, but also on the role of m7G in the digestive system, including digestive system tumors and non-tumor diseases." (PMID 39850560, 2024). "Studies have indicated that silencing METTL1/WDR4 suppresses HCC progression, while its expression promotes tumour proliferation, migration, and invasion." (PMID 38943267, 2024). "In a murine HCC model, sublethal heating predominantly promoted TGF-β production by upregulating METTL1 in tumor cells, resulting in the increased accumulation of MDSCs, reduced CD8+ T cell population, and enhanced tumor growth and metastasis." (PMID 36831664, 2023). "To evaluate the clinical relevance of METTL1 and WDR4 in patients with BC, we performed IHC analysis of the METTL1 and WDR4 proteins with TMAs, quantifying the positive staining of tumor cells." (PMID 37868988, 2023). "METTL1 (respectively the METTL1/WDR4 complex) has shown pro-oncogenic and tumor-suppressive activity within oncological research." (PMID 37275549, 2023). "To verify the accuracy of the sequencing results, we obtained tumor tissues and extracted mRNA and protein from HSPC and CRPC patients, and examined the differential expression of METTL1 at the mRNA and protein levels, respectively." (PMID 37599359, 2023). "We found a positive and significant correlation between METTL1 and WDR4 expression and PI3K enhanced pathway activation, indicating that METTL1 and WDR4 expression is increased in advanced PCa tumours." (PMID 37516825, 2023). "To determine the roles of METTL1 in facilitating CRPC progression in vivo, we used immunodeficient nude mice for subcutaneous transplantation tumor experiments." (PMID 37599359, 2023). "In HNSCC, knockdown of METTL1 altered both the composition of immune cells in the TME and how they communicate with tumor cells." (PMID 37710294, 2023). "The tumorigenicity of mice injected with METTL1-knockdown BE2C cells was suppressed compared to controls, as reflected by a significant decrease in tumor size and weight." (PMID 36071474, 2022). "For example, METTL1 and WDR4 serve as tumor promoters, resulting in tumor growth, invasion and metastasis in hepatocarcinoma, esophageal squamous cell carcinoma, glioma, head and neck squamous cell carcinoma and non-small cell lung cancer." (PMID 36358764, 2022).
tumor (continued). "Another study using CRISPR/Cas9 technology to construct liver-specific METTL1 knockout mice showed a significant reduction in HCC tumor lesions and a significant decrease in tumor load." (PMID 36120301, 2022). "The high expression of METTL1 and WDR4 is not only related to advanced tumor stage and grade but also to poor clinical outcome in patients with HCC." (PMID 35590385, 2022). "The inhibition of METTL1 and WDR4 weakens tumorigenesis of NPC, which significantly restrains the tumor growth, migratory, and invasion features, and increases cell apoptosis both in vivo and in vitro." (PMID 35590385, 2022). "METTL1 and WDR4 carry out tumor-promoting functions, enhancing the growth, migration, and invasion of ICC cells." (PMID 35590385, 2022). "For LIHC, METTL1, the key component of the m7G methyltransferase complex, was disclosed to be upregulated in LIHC and can promote tumor progression via m7G tRNA modification-dependent translation control." (PMID 35938009, 2022). "Firstly, the expression of METTL1 and WDR4 is significantly increased at both the mRNA and protein levels in ICC as compared with that in peri-tumor tissues, and these also act as poor survival predictors in ICC patients." (PMID 35590385, 2022). "Xenograft mouse model revealed that METTL1 overexpression significantly promoted the ESCC progression in vivo, as revealed by the increased tumor volumes/weights and upregulated Ki67 levels." (PMID 35304469, 2022). "The protein expressions of METTL1, NSUN2, EIF4G3, LARP1, NCBP1, and NCBP2 were higher in tumor tissues than in normal tissues; however, the protein expressions of WDR4, EIF4E1B, and NCBP2L were negative in both tumor and normal tissues." (PMID 35785179, 2022). "High mutation rates of METTL1 and WDR4 showed significant correlations in certain tumors, and the combination of the two biomarkers could be used to construct a precise model for predicting tumor progression and response to immunotherapy in BRCA, STAD, and LGG." (PMID 36226166, 2022). "Inhibition of METTL1 or WDR4 is an effective method to decrease ESCC progression both in vitro and in vivo, including impairing tumor proliferative capacity and tumor formation." (PMID 35590385, 2022). "We again found that a small number of METTLs, including METTL1 and METTL2A, were significantly elevated, while METTL7A was significantly decreased at the protein level in tumor tissue compared to NATs." (PMID 34285249, 2021). "Differences in mRNA and protein expression levels in METTL1 and METTL7A were observed according to LUAD tumor grade." (PMID 34285249, 2021). "Consistent with these, our western blot showed that m7G tRNA methyltransferase complex proteins METTL1 and WDR412, 31 were upregulated in HCC tumour tissues and cell lines." (PMID 34898034, 2021). "Accordingly, we also computed the correlation between CERES score of METTL1 and other genes in CRISPR/Cas9 screens of 808 tumor lines." (PMID 34285249, 2021). "A significant correlation between METTL1 expression and TMB was observed in multiple tumor types, specifically in LGG." (PMID 34838021, 2021). "Additionally, in vivo experiments demonstrated that tumor growth following HSC-1 and A431 cell implantation was suppressed upon METTL1 deletion." (PMID 39870616, 2025). "METTL1 expression was also similarly markedly upregulated metastasis and recurrence tumor compared with primary and no-recurrence tumor in GSE46517, another independent SKCM cohort dataset." (PMID 40443650, 2025). "The administration of the vaginal metabolite 5-formamidoimidazole-4-carboxamide ribotide to HGSOC cells and xenografted tumor models in nude mice resulted in the inhibition of cell proliferation and tumor growth of HGSOC, which was achieved by the inhibition of the METTL1/BRCA1 axis." (PMID 41430564, 2025).
tumor (continued). "Overall, our study underscores the significance of METTL1 and its role in the m7G modification of ATF4 as a means of regulating cSCC tumor progression, offering a foundation for the further exploration of innovative therapeutic approaches to clinical cSCC treatment." (PMID 39870616, 2025). "METTL1 regulates gene expression in stromal cells: in CRC, METTL1 modulates the expression of PKM2 through m7G mRNA modification, thereby promoting metabolic reprogramming and immune escape in tumor cells." (PMID 40809384, 2025). "Additionally, METTL1 catalyses m7G modification on mRNA, promoting mRNA stability, increasing NEK1 expression and facilitating tumour cell proliferation." (PMID 41208200, 2025). "Similarly, elevated METTL1‐mediated m7G tRNA modification has been detected in HCC tissues, reinforcing the importance of aberrant m7G methylation in tumour progression." (PMID 41208200, 2025). "In addition, the expression level of METTL1 was positively correlated with that of WDR4 and TNF-α in PTC tumor tissues, and WDR4 expression was also positively correlated with TNF-α expression." (PMID 40360483, 2025). "Furthermore, tissue microarray analysis confirmed a significant positive correlation among METTL1, its cofactor WDR4, and TNF-α expression levels in PTC tissues, highlighting their cooperative role in driving tumor aggressiveness." (PMID 41562049, 2025). "This evidence suggested that METTL1 might reduce the chance of cytotoxic T cells killing the tumor by inhibiting the infiltration of CD8+ T into the tumor, thereby promoting tumor progression." (PMID 40443650, 2025). "The increased cytotoxicity and therapeutic resistance of tumor cells upon METTL1 inhibition are not exclusive to PCa and ESCC." (PMID 38476632, 2024). "Furthermore, METTL1 and the HIST family of proteins have been found to be overexpressed mostly in tumor samples." (PMID 38893088, 2024). "To figure out the change of METTL1 expression in LUAD, we compared the gene expression difference between tumor and pericarcinomatous tissue using GEPIA, which includes the data form Genotype‐tissue expression (GTEx) and the Cancer Genome Atlas (TCGA), and GSE31210 dataset." (PMID 38967523, 2024). "In an HNSCC mouse model, Mettl1 depletion led to an increase in the infiltration of M1-like macrophages and Langerhans cells (LCs), and a reduced presence of regulatory T cells and CD4+ exhaustion cells within the tumor." (PMID 38476632, 2024). "In addition, the tumor survival dependence of WDR4, the METTL1 methyltransferase partner, is not only significantly correlated with that of METTL1, but also shows close relationship with these pathways." (PMID 39198433, 2024). "To confirm whether METTL1 and WDR4 expression could correlate with advanced tumour status, we measured PI3K pathway activity by phosphorylation status of S6K, which altered in in approximately 70% of patients with advanced PCa." (PMID 37516825, 2023). "Our results showed that the elimination of CD8+ T cells led to a significant increase in the size of only anterior lobe tumours lacking Mettl1." (PMID 37516825, 2023). "Moreover, METTL1 overexpression in HCC correlated with low expression of the tumor suppressor PTEN, increased tumor size, tumor vascular invasion, higher serum Alpha-Fetoprotein (AFP) level, and poor prognosis." (PMID 37612540, 2023). "Notably, three METTLs (METTL1, METTL7B, METTL27) were over-expressed in at least three of 15 TCGA tumor types compared to normal samples." (PMID 34285249, 2021). "Knockin of Mettl1 in mice cannot induce hepatocarcinogenesis in liver, suggesting that Mettl1 overexpression is not strong enough to drive tumour formation." (PMID 34898034, 2021). "Methyltransferase-like 1 (METTL1) was crucial for RNA processing (splicing, stability and localization) in a 7-methylguanosine (m7G) dependent manner, which served as a tumor suppressor and participated in the development of multiple cancers." (PMID 31866582, 2019).
tumor (continued). "Notably, mRNA levels of LARP1, METTL1, WDR4, and NCBP1 were upregulated in tumor specimens." (PMID 40485623, 2025). "Elevated METTL1 expression in tumor cells increases their sensitivity to specific chemotherapeutic drugs that target chromatin histone methylation, as well as the ERK–MAPK and WNT signaling pathways, suggesting METTL1 as a potential biomarker for drug sensitivity." (PMID 39802639, 2025). "RNA modifications can be catalyzed, erased and recognized by methyltransferases such as METTL1, METTL3, METTL16, and accurately regulate the process of methylation, which plays an important role in the proliferation, metastasis, invasion, apoptosis, autophagy, and drug-resistance of tumor cells." (PMID 40443650, 2025). "Similarly, Preclinical data demonstrate that pharmacological inhibition of METTL1 using METTL1-WDR4-IN-1, in combination with the PKM2 inhibitor shikonin, significantly impairs tumor growth in murine CRC models, with greater efficacy observed than with either agent alone ​." (PMID 40859309, 2025). "Consistent with its oncogenic role, METTL1 was reported to facilitate A549 cell proliferation and induce autophagy through upregulation of the AKT/ mechanistic target of rapamycin complex 1 (mTORC1) axis, highlighting its contribution to tumour growth and metabolic adaptation." (PMID 41208200, 2025). "However, inhibitors against m7G modifications have not been found to be effective, so the targeting of METTL1 for tumor treatment is not yet feasible, and our study is slightly limited in terms of clinical translation." (PMID 40360483, 2025). "For instance, studies in lung cancer have illustrated that overexpression of METTL1 and WDR4 stabilizes m7G-modified tRNA ValAAC and ProAGG, consequently promoting the translation of genes involved in cell-cycle regulation, thereby influencing tumor progression and prognosis." (PMID 38385078, 2024). "The METTL1/WDR4 complex performs m7G modification at position 46 of the tRNA ring to enhance mRNA translation by weakening ribosome suspension, thereby regulating self-renewal and differentiation of embryonic stem cells and playing a role in promoting tumor progression." (PMID 39850560, 2024). "The classification of tumor cells into subgroups and the identification of METTL1 as a therapeutic target are based on observational data, which may not fully capture the complex interactions within the tumor microenvironment." (PMID 38693422, 2024). "In addition, METTL1 and WDR4 drive drug resistance by altering the tumor microenvironment." (PMID 37710294, 2023). "Of note, previous studies identified that Wdr4 exerts multiple functions, such as regulating tumor microenvironments, stabilizing tRNA, and maintaining genome stability, through interacting with different partners/effectors, including DDB1/PML, METTL1, and FEN1, individually." (PMID 36681682, 2023). "In human beings, methyltransferase-like 1 (METTL1) and the WD repeat domain 4 (WDR4) are the most well-studied regulators of m7G, and have been reported to participate in tumor progression by regulating tumor immunity, metabolic reprogramming, and drug resistance." (PMID 36428620, 2022). "Consequently, we speculated an important regulation axis in BCa that METTL1 promoted the processing of miR-760 in an m7G modification-dependent way and contributed to degradation of ATF3 mRNA, accelerating the tumor growth and metastasis eventually." (PMID 36396627, 2022). "Moreover, histological analysis revealed that tumours in the Mettl1‐KI mice have higher percentage of Ki67‐positive cells and increased intensity of HCC marker AFP, suggesting the higher proliferative activity in the tumours from the KI mice." (PMID 34898034, 2021). "Moreover, massive tumour proliferation and neovascularization were observed in the tails of control group zebrafish, but not in zebrafish from the METTL1‐depleted group, on the 5th day after injection." (PMID 34936728, 2021).
tumor (continued). "In addition, METTL1 promotes the malignant phenotypes of proliferation, migration, and invasion in SKCM, and may also impede the infiltration of CD8+ T cells into the interior of the tumor by enhancing the communication between tumor cells and fibroblasts and thus forming a physical barrier." (PMID 40443650, 2025). "Based on the hormonal dependency of PCa tumours, expression analysis of METTL1, WDR4 and AR was performed, but no significative correlation was found between METTL1, WDR4 and AR expression." (PMID 37516825, 2023). "In their study, they discovered that METTL1 was overexpressed in the MCF7 cell line; however, further researches about the influence on tumor biological functions have not been performed." (PMID 36199792, 2022). "Meanwhile, m7G regulators are also downregulated in some tumors; for example, METTL1 is downregulated in CC samples as compared with adjacent normal tissues, and WBSCR22 exhibits a lower expression level in PC as compared with peri-tumor samples." (PMID 35590385, 2022). "However, no obvious differences in the expression levels of METTL1 and WDR4 were observed with respect to tumor stage and lymph node metastasis." (PMID 38822363, 2024).
digestive diseases (1 paper, 2024). "The METTL1/WDR4 complex can methylate mRNA, tRNA, and miRNA and affect translation, thus playing a role in digestive diseases." (PMID 39850560, 2024). "This review will focus on the latest research progress on the roles of m7G methyltransferase METTL1/WDR4 and recognized enzyme QKI in digestive diseases." (PMID 39850560, 2024). "By modulating the activity of methyltransferases such as METTL1 or WDR4, the level of m7G modification can be altered, thereby regulating the expression of related genes and cellular functions, and offering new hope for the treatment of digestive diseases." (PMID 39850560, 2024).
infection (1 paper, 2023). The state of being infected such as from the introduction of a foreign agent such as serum, vaccine, antigenic substance or organism. "METTL1, METTL21B, and CYP27B1 involve in vitamin D‐mediated antibacterial activity, which is a key signaling associated with infection." (PMID 38020709, 2023).
METTL1 also shares sentences with these, for which no sentence is quoted: sarcoma (3 papers); squamous cell carcinoma (3); degenerative diseases (2); digestive system tumors (2); liposarcoma (2); lung squamous cell carcinoma (2); mesothelioma (2); thymoma (2); thyroid cancer (2); acute myocardial infarction (1); asthma (1); bile duct cancer (1); bladder urothelial carcinoma (1); blood cancer (1); breast tumors (1); cardiovascular diseases (1); Chronic colitis (1); colon adenocarcinoma (1); cutaneous squamous cell carcinoma (1); esophageal adenocarcinoma (1); fatty liver disease (1); Galloway-Mowat syndrome (1); hypertrophy (1); infectious disease (1); mastitis (1); melanoma (1); microcephalic primordial dwarfism (1); neurodevelopmental disorder (1); pancreatic adenocarcinoma (1); pancreatic cancer (1).
A further 9 diseases each share a sentence with METTL1 in 1 paper.